STK4 (serine/threonine kinase 4)
Description:
Stress-activated, pro-apoptotic kinase which, following caspase-cleavage, enters the nucleus and induces chromatin condensation followed by internucleosomal DNA fragmentation. Key component of the Hippo signaling pathway which plays a pivotal role in organ size control and tumor suppression by restricting proliferation and promoting apoptosis. The core of this pathway is composed of a kinase cascade wherein STK3/MST2 and STK4/MST1, in complex with its regulatory protein SAV1, phosphorylates and activates LATS1/2 in complex with its regulatory protein MOB1, which in turn phosphorylates and inactivates YAP1 oncoprotein and WWTR1/TAZ. Phosphorylation of YAP1 by LATS2 inhibits its translocation into the nucleus to regulate cellular genes important for cell proliferation, cell death, and cell migration. STK3/MST2 and STK4/MST1 are required to repress proliferation of mature hepatocytes, to prevent activation of facultative adult liver stem cells (oval cells), and to inhibit tumor formation (By similarity). Phosphorylates 'Ser-14' of histone H2B (H2BS14ph) during apoptosis. Phosphorylates FOXO3 upon oxidative stress, which results in its nuclear translocation and cell death initiation. Phosphorylates MOBKL1A, MOBKL1B and RASSF2. Phosphorylates TNNI3 (cardiac Tn-I) and alters its binding affinity to TNNC1 (cardiac Tn-C) and TNNT2 (cardiac Tn-T). Phosphorylates FOXO1 on 'Ser-212' and regulates its activation and stimulates transcription of PMAIP1 in a FOXO1-dependent manner. Acts as an inhibitor of PKB/AKT1. Phosphorylates AR on 'Ser-650' and suppresses its activity by intersecting with PKB/AKT1 signaling and antagonizing formation of AR-chromatin complexes.
Synonyms: KRS2; MST1; YSK3
Tractability: Small molecule: a structure with a bound ligand is known; a high-quality ligand is known; it has a binding pocket of medium quality; it belongs to a druggable protein family. PROTAC: it is named in the literature on targeted protein degradation; ubiquitination databases record sites on it; its protein half-life has been measured; a small molecule that binds it is known.
Target class: Enzyme; Kinase; Protein Kinase; STE protein kinase STE20 family; STE protein kinase group; STE protein kinase MST subfamily
Safety:
Unwanted effects reported when the protein is acted on. In parentheses: how it was acted on, where the effect was seen, and who reports it.
cardiac arrhythmia (cardiovascular system; source: Lamore et al. (2017))
Gene: Protein-coding gene on chromosome 20 (44,966,494 to 45,084,214, forward strand). Ensembl gene ENSG00000101109.
Subcellular location: Cytoplasm; Nucleus
Subcellular location (Human Protein Atlas): Nuclear bodies; Cytosol; Nucleoplasm
Pathways (Reactome):
Signal Transduction: Signaling by Hippo
Gene Ontology:
Molecular function: ATP binding; identical protein binding; magnesium ion binding; protein binding; protein homodimerization activity; protein kinase activity; protein serine kinase activity; protein serine/threonine kinase activity; RNA polymerase II-specific DNA-binding transcription factor binding; protein serine/threonine kinase activator activity
Biological process: apoptotic process; cell morphogenesis; hippo signaling; intracellular signal transduction; negative regulation of canonical Wnt signaling pathway; peptidyl-serine phosphorylation; positive regulation of apoptotic process; positive regulation of hippo signaling; positive regulation of peptidyl-serine phosphorylation; positive regulation of protein phosphorylation; protein autophosphorylation; protein import into nucleus; protein phosphorylation; protein stabilization; regulation of MAPK cascade; signal transduction; anatomical structure morphogenesis; positive regulation of substrate-dependent cell migration, cell attachment to substrate; protein tetramerization
Cellular component: cytoplasm; cytosol; nuclear body; nucleoplasm; nucleus; protein-containing complex
Genetic constraint (gnomAD): Loss-of-function variants: 26 observed, 60.09 expected, observed/expected ratio (o/e) 0.43, 90% interval 0.32 to 0.6. The upper end of that interval is the gene's LOEUF score, 0.6, which puts it in group 2 of 6, group 1 being the genes least tolerant of losing a copy. Missense variants: 444 observed, 599.12 expected, observed/expected ratio (o/e) 0.74, 90% interval 0.69 to 0.8. Synonymous variants: 166 observed, 199.05 expected, observed/expected ratio (o/e) 0.83, 90% interval 0.73 to 0.95.
Gene-disease validity (ClinGen):
ClinGen rates the evidence that STK4 causes each of these diseases.
combined immunodeficiency due to STK4 deficiency (autosomal recessive): Definitive. A rare, genetic combined T and B cell immunodeficiency characterized by T- and B-cell lymphopenia, hypergammaglobulinemia and intermittent neutropenia.
Homologues: Orthologues: chimpanzee STK4 (99% identical), macaque STK4 (99% identical), guinea pig STK4 (98% identical), pig STK4 (98% identical), mouse Stk4 (97% identical), rabbit STK4 (97% identical), rat Stk4 (94% identical), dog STK4 (88% identical), tropical clawed frog stk4 (75% identical). Paralogues in human: STK3 (78% identical), TNIK (42% identical), MAP4K4 (41% identical), MINK1 (39% identical), SLK (33% identical), STK10 (33% identical), NRK (33% identical), STK24 (32% identical), STK25 (32% identical), STK26 (32% identical), MAP4K3 (31% identical), MAP4K5 (31% identical), and 23 more.
Diseases named in the same sentence as STK4 in open-access papers:
STK4 is named in the same sentence as 114 diseases in open-access papers, as found by Europe PMC text mining. Sharing a sentence is not in itself a finding about the gene and the disease. The quoted sentences say what the papers report.
Immunodeficiency (13 papers, 2016 to 2025). Failure of the immune system to protect the body adequately from infection, due to the absence or insufficiency of some component process or substance. "STK4 deficiency can cause combined immune deficiency, but this patient had only mild skin phenotypes and EBV viremia, with no lymphoproliferative disorders or neutropenia." (PMID 39110273, 2024). "STK4 deficiency causes a combined immunodeficiency characterized by a broad infectious susceptibility to bacteria, viruses, and fungi." (PMID 39339890, 2024). "Human serine/threonine kinase 4 (STK4) deficiency is a rare, autosomal recessive genetic disorder leading to combined immunodeficiency; however, the extent to which immune signaling and host defense are impaired is unclear." (PMID 34427831, 2021). "Human serine/threonine kinase 4 (STK4) deficiency is a rare autosomal recessive (AR) genetic disorder leading to combined immunodeficiency with severe T cell lymphopenia." (PMID 34427831, 2021). "Interestingly, NT5E and STK4 deficiency in humans has been reported as associating with combined immunodeficiency and recurrent infections." (PMID 37528081, 2023). "Several immunodeficiency disorders associated with EBV lymphoproliferation have been described, including deficiency of ITK, XIAP, STK4, SH2D1A, and CD27." (PMID 27338827, 2016). "MHC Class II defect and defects in STIM1, DOCK2, SP110, ZAP70, and STK4 genes are categorized as combined immunodeficiencies as per the 2019 International Union of Immunological Societies Expert Committee classification of human inborn errors of immunity (IEI)." (PMID 33628209, 2020). "Notably, STK4 deficiency was identified in three patients, a gene for combined immunodeficiencies; this type of entity is increasingly recognized in CVID-like phenotypes with combined immunodeficiency features." (PMID 40703516, 2025). "Importantly, no mutations were detected in other known EV-associated or immunodeficiency-related genes, such as RHOH, IL7, CORO1A, STK4, DOCK8, or CARMIL2, supporting the notion that the identified TMC6 and TMC8 variants may represent the primary genetic contributors in this case." (PMID 40534698, 2025).
lymphopenia (9 papers, 2017 to 2024). Reduction in the number of lymphocytes. "We have found one family with Molluscum lesions, pulmonary diseases and COPA deficiency; one patient with HPV lesions, monocytopenia and GATA2 deficiency and two families with HPV lesions, either EV or common warts, lymphopenia and STK4 deficiency." (PMID 37317175, 2023). "Patients with STK4/MST1 deficiency have a profound CD4 lymphopenia with very low circulating naive CD4 and CD8 T cells." (PMID 34867982, 2021). "T- and B-cell lymphopenia and neutropenia are reported as immunophenotyping phenotype of STK4 deficient patients." (PMID 32118703, 2020). "Serine/threonine kinase 4 (STK4) deficiency is an autosomal recessive genetic condition that leads to primary immunodeficiency (PID) typically characterized by lymphopenia, recurrent infections and Epstein Barr Virus (EBV) induced lymphoproliferation and -lymphoma." (PMID 30386345, 2018). "In conclusion, we report a patient with STK4 deficiency diagnosed in his thirties, with HPV38-associated EV, CD4+ lymphopenia, lymphoma and EBV viremia." (PMID 39110273, 2024). "STK4/MST1-deficient mice were shown to accumulate mature thymocytes in the thymus, which was associated with peripheral T cell lymphopenia." (PMID 34867982, 2021). "Patients with STK4 and GATA2 deficiencies, reported in this series, have similar clinical and immunological phenotypes than the previous ones: susceptibility to HPVs, T cells lymphopenia and monocytopenia, respectively." (PMID 37317175, 2023). "On the other hand, CD4+ T cell lymphopenia has also been reported in STK4-deficient patients in the absence of detectable EBV infection." (PMID 34427831, 2021). "Human serine-threonine kinase 4 (STK4) deficiency affects the immune system with recurrent bacterial and viral infections, mucocutaneous candidiasis, cutaneous warts, skin abscesses, T- and B-cell lymphopenia, and neutropenia." (PMID 32118703, 2020). "Clinical phenotype of eczema, AIHA, and CD4 lymphopenia noted in STK4 defect (pt." (PMID 33628209, 2020). "In addition, a possibly underlying STK4 deficiency should be suspected and tested in patients with a clinical history of recurrent infections, CD4 lymphopenia and lymphoma and unknown genetic make-up." (PMID 30386345, 2018). "In humans, studies have indicated that patients lacking STK4, which is a closely related paralog of STK3, showed T- and B-cell lymphopenia and recurrent bacterial and viral infections." (PMID 29226127, 2017).
breast cancer (7 papers, 2017 to 2025). A primary or metastatic malignant neoplasm involving the breast. "Our results align with these findings, as we observed consistent STK4 downregulation across all breast cancer subtypes." (PMID 41153630, 2025). "Particularly, in the reconstructed SYK signaling network, the proximal network of YAP1 and STK4, two Hippo pathway proteins, is almost entirely exclusive to breast cancer cells." (PMID 33670716, 2021). "Almost all interactions were breast cancer-exclusive, whereas two STK4 interactions originating from the Ras signaling pathway were DG75-exclusive." (PMID 33670716, 2021). "This resulted in decreased STK4 expression and promotion of breast cancer cell growth." (PMID 41153630, 2025). "In HER2-positive luminal B breast cancer, reduced STK4 expression was correlated with decreased OS." (PMID 41153630, 2025). "The subsequent step involved evaluating whether BIRC5, FGF1, RASSF6, SERPINE1 and STK4 could serve as targets for miRNAs differentiating breast cancer from the control." (PMID 41153630, 2025). "We found that MTORT1 could inhibit the proliferation and migration of breast cancer cells, and could serve as a miRNA sponge to up-regulate the nucleus-encoded genes, CREB1 and STK4, by binding to miR-26a-5p." (PMID 34141617, 2021). "Another hypermethylated and silenced gene in PTCL—serine/threonine-protein kinase 4 (STK4)—regulates cell differentiation and apoptosis and is the tumor suppressor in hepatocellular carcinoma, breast cancer, and lymphoma." (PMID 39189258, 2024). "Collectively, we have identified STK4 as a potential target of miR-522-3p regardless of breast cancer subtype." (PMID 41153630, 2025). "In luminal A breast cancer, reduced expression of RASSF6 and STK4 correlated with poorer OS." (PMID 41153630, 2025). "Although negative correlation between miR-26a-5p-CREB1 pair and miR-26a-5p - STK4 pair was observed in some cancers, there was no significant negative correlation in aggressive breast cancer tissues (data not shown)." (PMID 34141617, 2021).
lymphoma (7 papers, 2018 to 2024). A malignant (clonal) proliferation of B- lymphocytes or T- lymphocytes which involves the lymph nodes, bone marrow and/or extranodal sites. "Including this case, 33 patients with STK4 deficiency have been reported in total, 10 of whom had lymphoma." (PMID 39110273, 2024). "Interestingly, a recent report showed that STK4 plays a critical role as a tumor suppressor in the development of lymphoma and leukemia, putting STK4 deficient patients at an even higher risk to experience malignancies." (PMID 30386345, 2018). "Therefore, similar to other related disorders associated with EBV infections (such as MAGT1 or ITK deficiency), the lymphoma incidence in STK4 deficient patients is assumed to be increased although the absolute number of reported cases, including the case presented here is still low (n = 3)." (PMID 30386345, 2018). "Equally, MST1 - also known as serine/threonine kinase 4 (STK4) - has been described as critical factor for the maintenance of genomic integrity in lymphoma." (PMID 34615513, 2021). "STK4 deficiency is very susceptible to EBV infection, leading to lymphoid hyperplasia and lymphoma development." (PMID 32038526, 2019). "Case reports indicate that many patients with STK4 deficiency are highly susceptible to EBV infection, leading to lymphoid hyperplasia and lymphoma development." (PMID 32038526, 2019). "The mechanisms of STK4 in lymphoma suppression still need to be clarified and will most likely be complex due to the multiple essential functions of STK4 in e.g. apoptosis, autophagy, chromosome stability, cell cycle progression." (PMID 30386345, 2018). "We found that STK4 was significantly downregulated in all lymphoma datasets compared to healthy datasets indicating a tumor suppressive role of STK4." (PMID 30386345, 2018). "Due to the T cell impairment, many STK4-deficient patients experience fulminant EBV infections leading to lymphoproliferation and lymphoma development." (PMID 30386345, 2018). "STK4-deficient patients suffer from recurrent bacterial, fungal, and/or viral infections, including EBV-associated LPD, intermittent neutropenia, T and B cell lymphopenia, and increased risk of autoimmune diseases and lymphoma." (PMID 34638238, 2021). "We could confirm a significant general downregulation of STK4 in lymphomas derived from B- T- and NK cells." (PMID 30386345, 2018). "Our data suggests that patients with STK4 deficiency should be under close lymphoma surveillance even in the absence of EBV infections." (PMID 30386345, 2018). "Therefore, the lack of the antitumor capacities of STK4 should be considered as an additional risk factor in lymphoma development." (PMID 34638238, 2021). "Lymphoma development may be due to the lacking tumor suppressive function of STK4 or the perturbed immune surveillance due to the lack of CD4+ T cells." (PMID 30386345, 2018).
thyroid cancer (7 papers, 2019 to 2024). "STK4 was found to serve as a suppressor of thyroid cancer carcinogenic phenotypes in vitro such as proliferation, migration, and invasion through the induction of apoptotic pathways." (PMID 38672402, 2024). "Initial results revealed that circRNA_0057209 and STK4 were both reduced, while miR-183 was up-regulated in thyroid cancer tissues and cells." (PMID 35308166, 2022). "Altogether, findings obtained in our study indicated that circRNA_0057209 can potentially weaken the miR-183 binding ability to STK4 and activate the Hippo pathway, thus inhibiting the malignant development of thyroid cancer." (PMID 35308166, 2022). "STK4 is poorly expressed in human thyroid cancer cells; STK4 silencing promotes the proliferation of these cancer cells, inhibits apoptosis and autophagy, and thereby enhances tumor growth." (PMID 35409214, 2022). "Altogether, our findings indicated that circRNA_0057209 may serve as a competing endogenous RNA of miR-183 to increase STK4 expression, thus inhibiting the development of thyroid cancer." (PMID 35308166, 2022). "Besides, promotion of methylation of STK4 was previously shown to augment the apoptosis and autophagy of thyroid carcinoma cells." (PMID 35308166, 2022). "Of these, the serine/threonine kinase 4 (STK4) gene was a predicted output, which has been previously determined to have a significant role in thyroid cancer metastasis through the Hippo pathway." (PMID 38672402, 2024). "Using StarBase v2.0, several binding sites of hsa-miR-183 and STK4 were identified, further confirmed by a negative expression correlation in thyroid cancer patient cohorts." (PMID 38672402, 2024). "In addition, the overexpression of STK4 in MDA-T32 cells, a thyroid cancer cell line, induces cancer cell death by increasing mitochondrial stress, similar to that observed in YAP knockdown." (PMID 35409214, 2022).
Autoimmunity (6 papers, 2021 to 2024). The occurrence of an immune reaction against the organism's own cells or tissues. "Diseases associated with loss-of STK4 include T-cell immunodeficiency, recurrent infections, autoimmunity and cancer progression." (PMID 37019990, 2023). "The autoimmunity in STK4 deficiency may also be due to the defective regulation of development and function of regulatory T cells through modulation of FOXO1/FOXO3." (PMID 39339890, 2024). "Mutations in STK4 (MST1) are implicated in a form of autosomal recessive combined immunodeficiency, resulting in recurrent infections (especially Epstein-Barr virus viremia), autoimmunity, and cardiac malformations." (PMID 38361950, 2024).
prostate carcinoma (6 papers, 2010 to 2022). A carcinoma that arises from epithelial cells of the prostate gland. "We focused on miR-18a, as this can regulate STK4 gene expression in prostate cancer and miR-18a is highly expressed in invasive cervical cancer cells." (PMID 32555725, 2020). "This study further investigated the associations among miR-18a, STK4 and AKT and confirmed that miR-18a enhanced AKT phosphorylation by decreasing STK4 levels in prostate cancer cells." (PMID 31873828, 2019). "Overexpression of miR-18a in prostate cancer cells decreased STK4 protein expression and enhanced colony formation." (PMID 31873828, 2019). "Here, we investigated the effects of STK4, primarily localized in the cytoplasm, lipid raft, and nucleus, on cell growth and gene expression in aggressive prostate cancer." (PMID 28880957, 2017). "Previously, we identified STK4 as a binding partner of AKT protein complexes that were isolated from lipid raft of the androgen-sensitive LNCaP prostate cancer (PC) cell line." (PMID 28880957, 2017). "By targeting miR-18a, inhibiting the miR-18a/STK4 interaction or restoring STK4 expression, new miR-18a-related therapeutic strategies could be applied to future prostate cancer treatment." (PMID 31873828, 2019). "One study showed that the 3′-UTR of serine/threonine-protein kinase 4 (STK4) is a direct target of miR-18a, which is highly expressed in prostate cancer cell lines." (PMID 31873828, 2019). "To determine the mechanism by which STK4/MST1 signaling controls EPHA3 expression, we first assessed the abundance of the Ephrin A (EphA) and Ephrin B (EphB) receptor subtypes and their respective ligands in the well-characterized human prostate cancer cell lines LNCaP, C4-2, 22Rv1, and PC3." (PMID 35264657, 2022).